ZKSCAN3 (zinc finger with KRAB and SCAN domains 3)
Diseases named in the same sentence as ZKSCAN3 in open-access papers (continued):
Sharing a sentence is not in itself a finding about the gene and the disease.
ovarian carcinoma (2 papers, 2025). A malignant neoplasm originating from the surface ovarian epithelium. "In epithelial ovarian cancer, ZKSCAN3 has shown a more complex oncogenic logic by forming a synergistic regulatory network with epidermal growth factor receptor (EGFR), which is a member of the receptor tyrosine kinase superfamily I." (PMID 40723888, 2025). "In this study, we identify that ZKSCAN3 is overexpressed in ovarian cancer by analyzing a large-scale proteomic study of ovarian cancer." (PMID 41393507, 2025). "Seventeen of these genes were downregulated in ZKSCAN3-KD cells, and two were upregulated, which indicated ZKSCAN3 played a role in activating gene expression in ovarian cancer cells." (PMID 41393507, 2025). "Analysis of patient sample proteomic quantitation data indicates that the ZKSCAN3 protein is overexpressed in ovarian cancer." (PMID 41393507, 2025). "Collectively, these data suggested ZKSCAN3 regulated the expression of cancer-related genes in ovarian cancer cells." (PMID 41393507, 2025). "Western blot showed ZKSCAN3-KD indeed decreased the HSPB1 protein level in three different ovarian cancer cell lines, which was consistent with the change in mRNA level." (PMID 41393507, 2025). "In this study, we find ZKSCAN3, a zinc-finger transcription factor, is overexpressed in ovarian cancer." (PMID 41393507, 2025). "In summary, these data establish HSPB1 as an effector of ZKSCAN3 that promotes ovarian cancer cell proliferation." (PMID 41393507, 2025). "We find that HSPB1 is required for the regulation of cell proliferation by ZKSCAN3 in ovarian cancer cells." (PMID 41393507, 2025). "We knocked down ZKSCAN3 with lentivirus-expressed shRNA in different ovarian cancer cells, including HEY, A2780, and CaOV3." (PMID 41393507, 2025). "We show that knocking down ZKSCAN3 significantly retards ovarian cancer cell proliferation." (PMID 41393507, 2025). "We show that ZKSCAN3 promotes ovarian cancer cell proliferation." (PMID 41393507, 2025). "We characterized ZKSCAN3 localization in HEY ovarian cancer cells." (PMID 41393507, 2025). "The fact that ZKSCAN3-KD caused a significant change in approximately 10% of all protein-coding genes indicated that ZKSCAN3 might have a significant role in ovarian cancer biology." (PMID 41393507, 2025). "We next asked how ZKSCAN3 promoted ovarian cancer cell proliferation." (PMID 41393507, 2025). "The result showed that ZKSCAN3 knockdown significantly inhibited ovarian cancer cell clonogenesis." (PMID 41393507, 2025). "In addition, we find that the regulation of HSPB1 contributes to ZKSCAN3 function in ovarian cancer." (PMID 41393507, 2025). "We first asked whether ZKSCAN3 is differentially expressed between ovarian cancer samples and normal samples." (PMID 41393507, 2025). "Collectively, these data show ZKSCAN3 promotes ovarian cancer cell proliferation." (PMID 41393507, 2025). "Therefore, it is reasonable to postulate that ZKSCAN3 and its downstream pathway could be potential targets for an ovarian cancer therapeutic target." (PMID 41393507, 2025). "It was unclear whether ZKSCAN3 plays a role in ovarian cancer." (PMID 41393507, 2025). "We further examined whether ZKSCAN3 promoted ovarian cancer growth with a mouse xenograft model." (PMID 41393507, 2025). "We examined whether ZKSCAN3 affected ovarian cancer cell proliferation." (PMID 41393507, 2025). "However, whether and how ZKSCAN3 has a role in ovarian cancer remains unknown." (PMID 41393507, 2025). "Furthermore, we confirmed ZKSCAN3 enrichment at HSPB1 with ChIP followed by qPCR in both HEY and A2780 ovarian cancer cell lines." (PMID 41393507, 2025). "To examine whether the relationship between ZKSCAN3 and HSPB1 was also present in ovarian cancer patient samples, we analyzed the CPTAC ovarian cancer cohort, which revealed a statistically significant positive correlation between HSPB1 protein level and ZKSCAN3 protein level (p < 0.01)." (PMID 41393507, 2025).
adenoma (1 paper, 2022). A neoplasm arising from the epithelium. "ZKSCAN3 could participate in the carcinogenic process in the early stages of the adenoma–carcinoma sequence and could induce CIN; thus, functioning as a tumor progression factor." (PMID 36012568, 2022). "Therefore, the aberrant high expression of ZKSCAN3 in adenomas is not caused by genetic changes, unlike that in advanced cancers." (PMID 36012568, 2022). "In addition, ZKSCAN3 expression was more prominent in the dysplastic epithelia of the adenomas." (PMID 36012568, 2022). "We compared ZKSCAN3 expression by performing ZKSCAN3 immunohistochemical staining for normal colon epithelium, non-neoplastic hyperplastic polyps, adenomas, and advanced cancers." (PMID 36012568, 2022). "Significant changes in the ZKSCAN3 gene copy numbers were observed only in advanced cancers and not in adenomas." (PMID 36012568, 2022). "We performed IHC using anti-ZKSCAN3 and anti-β-catenin antibodies in the contiguous sections of formalin-fixed paraffin-embedded (FFPE) tissues and examined the correlation between ZKSCAN3 and β-catenin expression in adenomas." (PMID 36012568, 2022). "Early upregulation of ZKSCAN3 in adenomas is not sufficient to drive the conversion of dysplastic adenoma to adenocarcinoma; however, this study indicates that ZKSCAN3 induces CIN and could play a crucial role in early stage carcinogenesis." (PMID 36012568, 2022). "The regulation of ZKSCAN3 expression through the Wnt/β-catenin signaling pathway could partially explain the reason for ZKSCAN3 upregulation in adenomas without increased gene copies and in adenocarcinomas." (PMID 36012568, 2022).
atherosclerosis (1 paper, 2025). A disease characterized by the build-up of fatty material and calcium deposition in the arterial wall resulting in partial or complete occlusion of the arterial lumen. "In a type 2 diabetes mellitus (T2DM)-related atherosclerosis (AS) model, Nε-carboxyethyl lysine (CEL) inhibited autophagy-related gene expression by promoting the nuclear localization of ZKSCAN3, leading to impaired macrophage autophagy and decreased plaque stability." (PMID 40723888, 2025).
bladder tumors (1 paper, 2016). "Next, we used mouse xenograft models to investigate the role of ZKSCAN3 in bladder tumor outgrowth in vivo." (PMID 27447553, 2016). "Correspondingly, the levels of ZKSCAN3 gene were significantly elevated in bladder tumors, compared with those in adjacent normal-appearing bladder mucosae (P=0.008)." (PMID 27447553, 2016). "Similar to the findings in these studies, we observed elevated expression of ZKSCAN3 mRNA and protein in bladder tumors, compared with control benign urothelial tissues." (PMID 27447553, 2016).
chronic obstructive pulmonary disease (1 paper, 2025). A chronic and progressive lung disorder characterized by the loss of elasticity of the bronchial tree and the air sacs, destruction of the air sacs wall, thickening of the bronchial wall, and mucous accumulation in the bronchial tree. "It is important to note that ZKSCAN3 is not only involved in the regulation of lung tissue growth and development but also correlates with the level of residual lung function in patients with chronic obstructive pulmonary disease (COPD)." (PMID 40723888, 2025).
colon adenoma (1 paper, 2022). An adenoma that arises from the colon. "ZKSCAN3 expression was correlated with that of β-catenin in colon adenomas." (PMID 36012568, 2022).
depression (1 paper, 2023). "Notably, TCF4, NKAPL, ZKSCAN3, ZSCAN16, ZSCAN31 have been associated with depression in previous GWASs." (PMID 36750733, 2023).
epilepsy (1 paper, 2026). A brain disorder characterized by episodes of abnormally increased neuronal discharge resulting in transient episodes of sensory or motor neurological dysfunction, or psychic dysfunction. "Nine shared genetic loci and six pleiotropic genes, including SCN1A, PGBD1, ZKSCAN3, ZKSCAN4, VRK2, and ZSCAN23, have been identified between epilepsy and psychiatric disorders." (PMID 41733899, 2026).
Immunodeficiency (1 paper, 2023). Failure of the immune system to protect the body adequately from infection, due to the absence or insufficiency of some component process or substance. "ZNF629 is known to cause immunodeficiency and ZKSCAN3 is a master repressor of autophagy." (PMID 38025778, 2023).
pancreatic cancer (1 paper, 2025). "This functional paradox suggests that targeting the ZKSCAN3-autophagy regulatory axis may provide a novel intervention strategy for pancreatic cancer treatment." (PMID 40723888, 2025). "Mechanistic studies have demonstrated that ZKSCAN3 inhibits pancreatic cancer cell proliferation, migration, and invasion by transcriptionally activating the expression of autophagy core genes, such as ULK1 and LC3-II, and promoting autophagosome formation and lysosomal degradation functions." (PMID 40723888, 2025).
Sepsis (1 paper, 2025). Sepsis is defined as life-threatening organ dysfunction caused by a dysregulated host response to infection. "Pathologic association of lung infection with sepsis reveals a central role for ZKSCAN3 in immunomodulation through regulation of the autophagy-lysosome pathway." (PMID 40723888, 2025). "In sepsis pathogenesis, ZKSCAN3 up-regulation suppresses LC3-II and LAMP1 expression, compromising lysosomal activity and pathogen clearance capacity." (PMID 40723888, 2025). "Together, these findings suggest that ZKSCAN3 is involved in the pathological process of immune imbalance and multi-organ damage after lung infection and sepsis by inhibiting lysosomal production and repair, providing a molecular basis for the development of targeted intervention strategies." (PMID 40723888, 2025).
urothelial neoplasm (1 paper, 2016). A neoplasm involving a urothelium. "Immunohistochemistry in tissue specimens detected ZKSCAN3 signals in 138 (93.2%) of 148 urothelial neoplasms, which was significantly higher than in non-neoplastic urothelial tissues [76 (84.4%) of 90; P=0.044]." (PMID 27447553, 2016). "We next stained immunohistochemically for ZKSCAN3 in a bladder tissue microarray (TMA) consisting of 148 urothelial neoplasm specimens and corresponding 90 non-neoplastic bladder tissues." (PMID 27447553, 2016).
tumor (19 papers, 2016 to 2025). "Specifically, ZKSCAN3 promotes tumor progression by enhancing multiple hallmark features of cancer and promoting the acquisition of cancer-specific phenotypes." (PMID 39519085, 2024). "ZKSCAN3 serves as a crucial factor in driving the proliferation of tumor cells, a hallmark of tumorigenesis that is often characterized by deregulated cell growth." (PMID 39519085, 2024). "In this review, we provide an updated perspective on the role of ZKSCAN3 in governing tumor characteristics and the underlying molecular mechanisms." (PMID 39519085, 2024). "Elevated expression levels of ZKSCAN3 have been documented across multiple cancer types, particularly in association with the accelerated growth of tumor cells." (PMID 39519085, 2024). "ZKSCAN3 encodes a zinc-finger transcription factor that regulates the expression of important genes and plays a significant role in tumor development, pathogenesis, and metastasis." (PMID 34940950, 2022). "Mechanistic details underlying the promotion of tumor development and progression by ZKSCAN3 also need to be further characterized." (PMID 27447553, 2016). "Research indicates that the WNT/β-catenin pathway induces ZKSCAN3 gene expression via the β-catenin/TCF4 complex, with ZKSCAN3 levels closely associated with the presence of β-catenin within the nucleus, thereby establishing a reinforcing cycle that promotes tumor progression." (PMID 40723888, 2025). "Furthermore, ZKSCAN3 expression exhibits a strong correlation with aggressive histopathological characteristics and an elevated risk of tumor recurrence, functioning as an independent predictive marker." (PMID 39519085, 2024). "In addition, ZKSCAN3 expression was found to strongly associate with more aggressive histopathological features and a higher risk of tumor recurrence as an independent predictor." (PMID 32824199, 2020). "Additionally, strong (2+/3+) ZKSCAN3 expression (p = 0.002), as an independent prognosticator, or vasectomy (p = 0.072) was associated with the risk of tumor recurrence." (PMID 32824199, 2020). "In these subgroups, ZKSCAN3 levels (0/1+ vs. 2+/3+: hazard ratio (HR) = 2.569, 95% confidence interval (CI) = 1.241–5.320, p = 0.011; 0/1+/2+ vs. 3+: HR = 1.766, 95% CI = 0.937–3.327, p = 0.079) were associated with the risk of tumor recurrence." (PMID 32824199, 2020). "Molecularly, ZKSCAN3 promotes tumor proliferation and angiogenesis and enhances metastatic potential through transcriptional activation of the expression of key genes such as VEGF, ITGβ4, and CCND D1/D2." (PMID 40723888, 2025). "Animal models further verified that ZKSCAN3-shRNA significantly inhibited graft tumor growth by suppressing the AKT/mTOR signaling axis." (PMID 40723888, 2025). "In most malignancies, nuclear accumulation of ZKSCAN3 suppresses autophagy to promote tumor proliferation and metastasis." (PMID 40723888, 2025). "ZKSCAN3 plays an important role in tumor progression by regulating key molecules such as VEGF, ITGβ4, MMP2, MMP9, CCND1, and CCND2." (PMID 40723888, 2025). "Specifically, hepatic metastatic tissue exhibits higher ZKSCAN3 protein expression compared to primary tumor tissue in patients with high serum CEA levels, while in patients with normal serum CEA, ZKSCAN3 expression either declines or remains comparable." (PMID 39519085, 2024). "Collectively, these findings establish a direct link between ZKSCAN3 and tumor progression and prognosis, indicating its potential as a biomarker for predicting malignant outcomes." (PMID 39519085, 2024). "This regulatory interaction suggests that ZKSCAN3 functions as a downstream mediator in the oncogenic pathways orchestrated by these transcription factors, thereby facilitating tumor growth, survival, and metastasis." (PMID 39519085, 2024). "Scientific validation underscores ZKSCAN3’s anti-tumor properties and its potential as a clinically significant prognostic factor in diverse human cancers." (PMID 39519085, 2024).
tumor (continued). "Overexpression of ZKSCAN3 has been observed across various cancers, where it promotes tumor growth by enhancing cellular proliferation and inhibiting programmed cell death mechanisms." (PMID 39519085, 2024). "Zinc finger containing KRAB and SCAN domains 3 (ZKSCAN3) was discovered to enhance tumor migration in different types of cancers, such as breast, colorectal, and prostate, except for GBM." (PMID 38214842, 2024). "We propose that their functions would also be similar and, along with ZKSCAN3, can be targeted for the development of tumour therapy." (PMID 35600335, 2022). "The wide expression of ZKSCAN3 in tumour cells makes it an important potential target for tumour therapy." (PMID 35600335, 2022). "In summary, these observations highlight a promoting role of ZKSCAN3 in tumor progression and metastasis, resulting in poor patient outcomes, which renders it a possible therapeutic target." (PMID 33672287, 2021). "As shown in the represented figures, CHD1L overexpression strongly induced metastatic tumor nodule formation in mice liver (5/5), whereas, this effect was impaired by overexpression of ZKSCAN3 (1/5)." (PMID 34654797, 2021). "Overexpression of CHD1L transcriptionally suppressed the expression of autophagy inhibitor ZKSCAN3, and accelerated autophagic degradation of Paxillin, which is crucial for dynamic disassembly of FA of tumor cells." (PMID 34654797, 2021). "In summary, we have identified a novel CHD1L/ZKSCAN3/Paxillin autophagic axis in regulating tumor cell migration and metastasis." (PMID 34654797, 2021). "CHD1L negatively controlled the transcription of ZKSCAN3 and prevented the inhibitory role of ZKSCAN3 in tumor cell autophagy." (PMID 34654797, 2021). "Patients with ZKSCAN3(2+/3+) (p = 0.002) or ZKSCAN3(3+) (p < 0.001) tumor had a significantly higher risk of biochemical recurrence after radical prostatectomy, compared to those with ZKSCAN3(0/1+) or ZKSCAN3(0/1+/2+) tumor, respectively." (PMID 32824199, 2020). "Similar to the mRNA level results, ZKSCAN3 protein was found to be strongly expressed in the nucleus of tumor cells from all 126 CC samples." (PMID 30241382, 2018). "The authors suggested that ZKSCAN3 regulates the expression of the genes favoring tumor progression." (PMID 30241382, 2018). "Paradoxically, ZKSCAN3 exhibits context-dependent oncogenic or tumor-suppressive activities." (PMID 40723888, 2025). "It is noteworthy that ZKSCAN3 also exhibits cross-system biological diversity by regulating lysosomal function, autophagy activity, and respiratory homeostasis, which further highlights its role in tumor microenvironment modulation." (PMID 40723888, 2025). "The result showed ZKSCAN3-KD significantly decreased tumor growth." (PMID 41393507, 2025). "On one hand, ZKSCAN3 binds and activates certain pro-tumor genes." (PMID 41393507, 2025). "ZKSCAN3 actively modulates the invasiveness and metastatic proclivity of tumor cells." (PMID 39519085, 2024). "Changes in the tumor microenvironment, such as alterations in the composition and stiffness of the extracellular matrix, can significantly influence stromal cell function and ZKSCAN3 expression." (PMID 39519085, 2024). "In the context of cancer, aberrant phosphorylation and ubiquitination of ZKSCAN3 can lead to altered transcriptional landscapes that facilitate tumor growth, survival, and metastasis by modulating genes implicated in cell cycle progression, apoptosis inhibition, and metabolic reprogramming." (PMID 39519085, 2024). "Additionally, the expression of ZKSCAN3 protein is elevated in hepatic metastatic tissue compared to primary tumor tissue in patients with high serum CEA levels, while it remains stable or decreases in those with normal levels." (PMID 39519085, 2024).